IL6 (interleukin 6)
Diseases named in the same sentence as IL6 in open-access papers (continued):
Sharing a sentence is not in itself a finding about the gene and the disease.
COVID-19 (continued). "In particular, an increased level of interleukin-6 has been shown to be associated with poor outcomes in patients with COVID-19." (PMID 33133323, 2020). "Blocking of CCR5 by leronlimab found to reduce serum IL-6 levels, which is linked with cytokine storm, in critical COVID-19 patients." (PMID 32973505, 2020). "CDCs target multiple cytokine pathways (e.g., TNFα, IFN-γ, IL-1β, IL-6) that are associated with disease progression and poor outcomes in COVID-19." (PMID 32399655, 2020). "In fact, the increased serum IL-6 levels in severe and critical COVID-19 patients is associated with poor outcomes, which was also observed during severe acute respiratory syndrome (SARS) outbreak." (PMID 32909961, 2020). "In patients infected with COVID-19, the presence of increased levels of serum inflammatory markers including IL-6, CRP, LDH, ferritin, and D-dimers has been associated with an increased risk of progression to more severe forms of the disease." (PMID 33133323, 2020). "A cytokine storm caused by COVID-19 increases circulating IL-6 levels in the body; hence, the proinflammatory effects, combined with a lack of renal ACE2 protection, leads to a severe functional injury to the kidneys." (PMID 33232272, 2020). "High levels of interferon (IFN)-α, IFN-γ–induced protein-10, monokine induced by IFN-γ, and interleukin-6 at 5–10 days from symptom onset were associated with the severity of COVID-19." (PMID 33124544, 2020). "Laboratory parameters such as neutrophil-to-lymphocyte ratio, C-reactive protein (CRP), interleukin (IL)-6 and dimer-D levels are reported as indicators of COVID-19 severity when associated to clinical features of the infection." (PMID 33178720, 2020). "Of these cytokines and chemokines, IL-6, which is produced by pathogenic T cells and monocytes, has attracted attention as a therapeutic target for severe cases of COVID-19." (PMID 32582401, 2020). "Both IL-6 and complement have been proposed as therapeutic targets and understanding their role in COVID-19-associated AKI is therefore a priority." (PMID 32880774, 2020). "The increase in IL-6 production was found to be an independent risk factor for the progression to critical illness among septic COVID-19 patients, which was consistent with the report by Wang and colleagues." (PMID 33178716, 2020). "The upregulation of ACE2 is associated with an increase in the levels of IL-1, IL-10, IL-6, and IL-8, which are important cytokines in the pathophysiology of COVID-19." (PMID 33072624, 2020). "PCR positive and negative patients did not display differences in oxygen saturation or in several analytical parameters associated with COVID-19, including low lymphocyte counts, high D-dimer levels or high IL-6 levels." (PMID 32708750, 2020). "More recently, a study found that levels of IL-6 in the cerebrospinal fluid of patients with COVID-19-associated neurological symptoms were greater than that of control subjects." (PMID 33120941, 2020). "Recently, Tocilizumab was incorporated as a treatment option in COVID-19 management guidelines to be used in severe or high-risk conditions with elevated concentrations of IL-6." (PMID 32922406, 2020). "The caveats and suboptimal outcomes associated with the clinical results from IL-1 and IL-6 blockade in preventing COVID-19 mortality raise important questions regarding the optimal target(s) and strategies to treat a cytokine storm." (PMID 32766256, 2020). "In the pathogenic of severe COVID-19 cases underlies a cytokine release syndrome (CRS) in which interleukin 6 (IL-6) plays a central role." (PMID 33042826, 2020). "An elevated Th1/Th2 ratio has been correlated to increased risk of mortality in COVID-19 patients as the proinflammatory cytokine IL-6 has been predictive for severe lung pathology." (PMID 32983176, 2020). "Another recent study reported that the serum SARS-CoV-2 viral load (RNAaemia) is strongly associated with the levels of IL-6 in COVID-19 patients." (PMID 33072097, 2020).
COVID-19 (continued). "Levels of serum IL-6 and IL-6 receptors (IL-6R) were significantly elevated in patients with COVID-19, and were closely associated with respiratory failure, acute respiratory distress syndrome, secondary infections, and death." (PMID 33384605, 2020). "Reduced COX-2 alongside high IL-6 and IP-10, as seen here in severe COVID-19 patients, is an immune profile associated with pathology in idiopathic pulmonary fibrosis (IPF)." (PMID 32943497, 2020). "COVID-19 is associated with both immunodeficiency and hyperinflammation, and T cell numbers are negatively correlated with serum IL-6, IL-10 and TNF-α." (PMID 33365277, 2020). "Elevated levels of pro-inflammatory cytokines, including IL-6 are associated with severe COVID-19 and an increase in IL-6 is associated with increased mortality." (PMID 33154972, 2020). "Abnormal concentrations of several associated cytokines like TNF, IL-10, and IL-6 were found in COVID-19 patients." (PMID 33224256, 2020). "It’s important to point here that both mild and severe forms of COVID-19 have been reported to be associated with changes in circulatory cytokine levels such as IL-6, IL-1β, and others." (PMID 33102489, 2020). "Tocilizumab can block the activity of proinflammatory interleukin-6 (IL-6), which is involved in the pathogenesis of pneumonia that causes death in COVID-19 patients." (PMID 32882868, 2020). "While awaiting a vaccine to constrain the pandemic, IL-6 blockade seems to be a rational therapeutic approach to contrast CRS associated with COVID-19." (PMID 32636755, 2020). "Specific inflammatory molecules such as TNFα, IL-6, and other inflammatory signaling pathways identified with COVID-19 have been associated with the pathogenesis of type 2 diabetes mellitus and malaria through insulin resistance." (PMID 33134395, 2020). "It should also be noted that observations of high circulating levels of IL-6 in COVID-19 patients can result in misled assumptions about the causal role of this cytokine in the pathogenesis of this disease." (PMID 33442386, 2020). "Activation of systemic inflammatory responses via an acute increase in pro-inflammatory cytokines, including interleukin-6 (IL-6) termed as Cytokine Storm, has been linked to disease severity and death in COVID-19 patients." (PMID 33613275, 2020). "As IL-6 is the most frequently reported cytokine to be increased in COVID-19 patients and as IL-6 elevated levels have been associated to higher mortalities, tocilizumab is a candidate drug to be used in managing the cytokine storm accompanying COVID-19." (PMID 32612617, 2020). "An earlier study reported that the detectable serum viral load of COVID-19 was closely associated with drastically increased IL-6 levels in the critically ill." (PMID 33134238, 2020). "Improving the understanding of hypercytokinemia (i.e., IL-6 levels from 100 to 5,000 pg/mL) and immune dysregulation associated with COVID-19 is urgent." (PMID 32793246, 2020). "Among the cytokines that are elevated in the cytokine storm in COVID-19, IL-6 is important because it is the most strongly associated cytokine with coronary heart disease (CHD)." (PMID 32733487, 2020). "The crucial involvement of IL-6 in COVID-19 is strengthened by a recent report that impaired immune cell cytotoxicity in severe COVID-19 is IL-6-dependent, underlining the importance of anti-IL-6 in combating severe COVID-19." (PMID 32806722, 2020). "Recent meta-analyses confirmed that elevated IL-6 levels are closely associated with the severity of COVID-19, further suggesting that IL6 genetic variants should be considered as a potential determinant of the host response against CoVs." (PMID 32917282, 2020). "Recently, the amplifying positive feedback loop between IL-6 / STATs and NF-κB signaling has been highlighted with regard to COVID-19 associated mortality." (PMID 33362782, 2020).
COVID-19 (continued). "The latest is one of the main outcomes of the hyperinflammation phase associated with severe COVID-19 cases supported by the concomitant upregulation of gal3, TNFα and IL-6 in lobar and bronchial pneumonia." (PMID 32973815, 2020). "As COVID-19 is linked with swift replication and a propensity to infect the lower respiratory tract, so it results in an increased response of IL-6-promoted severe respiratory distress." (PMID 33194800, 2020). "The cytokine storm has been widely reported to occur in severe COVID-19 and bacterial sepsis and many studies have shown that elevated levels of some cytokines, such as IL-6 and IL-10, are associated with mortality." (PMID 33329592, 2020). "The present study aimed to explore the kinetics of IL-6 levels, validate this association in COVID-19 patients, and report preliminary data on the efficacy of IL-6 receptor blockade." (PMID 33121497, 2020). "In another study of COVID-19 patients with elevated D-dimer levels, increased fibrinogen levels were also identified and associated with increased IL-6 levels." (PMID 32922297, 2020). "Elevated serum IL-6 has been observed in COVID-19 patients, with higher levels associated with more severe disease presentation and mortality." (PMID 33510644, 2020). "In patients with COVID-19 and obesity, the IL-6 and TNF-α high serum levels are negatively associated with T-cells." (PMID 33160363, 2020). "For instance, high levels of IL-1ra and IL-6 cytokines in plasma samples of COVID-19 patients demonstrate a clear association between the severity of the immune response and fatal outcome." (PMID 32973815, 2020). "Meanwhile, the presence of diabetes was positively associated with hs-CRP and IL-6 in the COVID-19 patients." (PMID 33062712, 2020). "Another study showed that elevated inflammatory blood markers, including IL-6, can serve as a predisposing factor for increased mortality from COVID-19, suggesting death from virus-activated ‘cytokine-storm syndrome’." (PMID 32916821, 2020). "High levels of plasmatic IL-6 have been consistently reported in COVID-19 and even appear to be associated with poor prognosis and risk of death." (PMID 32612615, 2020). "High serum IL-6 has also been found in older adults as part of the “inflamm-aging” phenotype, predisposing elders to more severe COVID-19 presentation." (PMID 33510644, 2020). "More importantly, our results showed that D-dimer levels positively correlated with increased PCT and IL-6 levels, adding evidence that severe inflammation associated with hypercoagulability in cancer patients with COVID-19." (PMID 32766161, 2020). "Tocilizumab blocks pro-inflammatory activity of interleukin-6 (IL-6), involved in pathogenesis of pneumonia the most frequent cause of death in COVID-19 patients." (PMID 33087150, 2020). "AAT modulates activities that result in downstream IL-6 inhibition, which is implicated in COVID-19 pathogenicity." (PMID 33276468, 2020). "In COVID-19 patients the severity of the disease is associated with a cytokine storm with markedly increased expression of interleukin 6 (IL-6) in the serum of severe cases." (PMID 32691695, 2020). "IL-6 is thought to be a key mediator of cytokine storm, causing tissue injury and the progression of COVID-19." (PMID 33384605, 2020). "Clinically reflected in life-threatening respiratory failure in COVID-19, elevated serum IL-6 is also associated with lymphopenia, functional T-cell deficiency, and vasculitis." (PMID 33233531, 2020). "Taken together, these findings suggest that IL-6 or its receptor present a potent target of interest for the treatment of COVID-19-associated acute respiratory distress syndrome (ARDS)." (PMID 32793246, 2020). "It is thereby likely that corticosteroids and IL-1 inhibition result in the inhibition of IL-6, as well as other mediators with a causative ole in the pathogenesis of COVID-19." (PMID 33442386, 2020).
COVID-19 (continued). "COVID-19 related publications were highly associated with IL-6, reflective of the empirical finding of IL-6 elevation in this disease that in turn relates to cytokine release syndrome mooted as a mechanism underlying more severe cases of the disease." (PMID 32746922, 2020). "The COVID-19 with CLD group showed an increased lymphocyte count as well as increased IL-6 and PCT levels, suggesting pathogenic effects from excessive inflammation in acute lung injury caused by COVID-19 infection." (PMID 32855361, 2020). "Persistent and dramatic elevation of serum IL-6 level was associated with higher mortality in COVID-19 patients." (PMID 32562070, 2020). "Factors associated with poor outcomes from COVID-19 are lymphopenia, high levels of D-dimer, cardiac troponin I, serum ferritin, lactate dehydrogenase and IL-6." (PMID 32933369, 2020). "Among various proinflammatory cytokines, IL-6 plays a major role in inducing ARDS as an increase in the concentration of IL-6 in the plasma was found to be linked with ARDS in COVID-19 patients." (PMID 32973505, 2020). "Tocilizumab, a monoclonal antibody against IL-6, emerged as an alternative treatment for COVID-19 patients with a risk of cytokine storms recently." (PMID 32854750, 2020). "The severe cases of COVID-19 with high mortality are associated with reduced innate and adaptive immune responses in conjunction with abundant cytokine and overexpression of interleukin 6 (IL-6)." (PMID 32607505, 2020). "In COVID-19 patients, a profile of cytokines, such as IL-2, IL-6, IL-7, INF-γ, and TNF-α, is associated with disease severity and mortality of patients." (PMID 33679608, 2020). "Interest in the use of tocilizumab, a monoclonal antibody against IL-6, in COVID-19 patients has emerged especially in those at risk of exaggerated inflammatory response." (PMID 32581799, 2020). "IL-6, a key inflammatory cytokine, has been implicated in the pathogenesis of severe COVID-19." (PMID 41773135, 2026). "This suggests that the IL-6/KL-6 ratio may be predictive of the severity of certain typical lung lesions associated with COVID-19 ARDS." (PMID 40397955, 2025). "COVID-19 can cause endothelial injury during the process of virus penetration and release, as well as through the release of cytokines, primarily interleukin-6 (IL-6), which exacerbates the process of thromboinflammation." (PMID 40172407, 2025). "While the link between diabetes and severe COVID-19 complications remains unclear, limited data suggest that markers such as interleukin (IL)-1, IL-6, C-reactive protein, and D-dimer are associated with COVID-19 severity in diabetic individuals." (PMID 40372276, 2025). "In fact, COVID-19-associated male infertility may involve a decrease in testosterone levels and spermatogenesis through shifts in cytokines such as IL-4, IL-6, IFNγ, and TNFα." (PMID 40507130, 2025). "Angiotensin II subsequently activates the nuclear factor kappa B (NF-κB) pathway, a key regulator of inflammation, which is also stimulated by other cytokines implicated in COVID-19, such as IL-1β, IL-6, TNF-α, IL-10, MCP-1, AT1, and platelet-derived growth factor beta (PDGF-B)." (PMID 40869200, 2025). "In COVID-19, elevated IL-6 levels are linked to greater disease severity." (PMID 41323348, 2025). "Particularly, the IL-6 levels observed in acute infections (e.g., COVID-19 patients) could reach approximately 70 pg/ml, while the aging-associated elevation of IL-6 is mild (e.g., ~ 3.5 pg/ml for men and ~ 2.1 pg/ml for women aged ≥ 85 years old)." (PMID 40770768, 2025). "Our study suggested that increased neutrophil counts might be associated with a previous increase in IL-6 levels in patients with COVID-19." (PMID 40002608, 2025). "Additionally, elevated levels of IL-17 and IL-6 significantly increased the risk factor of severe illness in COVID-19 patients by approximately 5.6- and 3.2-fold (p = 0.0003 and p = 0.011, respectively)." (PMID 41184328, 2025).
COVID-19 (continued). "Increased IL6 is associated with increased mortality in COVID-19 patients." (PMID 41157583, 2025). "Since high levels of IL-6 are linked with COVID-19 severity and mortality, the auranofin effect on NF-kB/IL-6/STAT3 cascade could be an advantage in the management of the infection." (PMID 40333653, 2025). "Moreover, higher levels of procalcitonin, ferritin, CRP, lactate dehydrogenase, interleukin-6, and D-dimer are linked to poor prognosis and high mortality risk for COVID-19 patients." (PMID 40766923, 2025). "That patients with MASLD might have different immune responses was shown in COVID-19, where several cytokines and chemokines were linked with uncontrolled inflammation and development of severe/critical disease (such as IL-6, IL-8, IL-10, TGF-β1 and CXCL10)." (PMID 40076848, 2025). "Elevated levels of IL-6, for example, are commonly associated with poor outcomes and may underlie the “cytokine storm” syndrome observed in severe COVID-19 cases." (PMID 40843708, 2025). "Additionally, sex, obesity, ethnicity, and pre-existing inflammatory conditions have been identified as risk factors for elevated IL-6 levels in COVID-19 patients." (PMID 40429727, 2025). "Similar to IL6R, we found genetic IL6 downregulation to be associated with lower risk of hospital admission due to sepsis and a sepsis diagnosis in individuals <75 years, as well as hospitalization due to COVID-19." (PMID 40858837, 2025). "Advanced age, comorbidities, and elevated IL-6 levels were associated with severe COVID-19." (PMID 40868247, 2025). "While elevated interleukin-6 (IL-6) levels are linked with severe COVID-19 and higher mortality, CF patients show lower IL-6 levels in their airway epithelia, which might offer protection against severe SARS-CoV-2 infection." (PMID 40733537, 2025). "High levels of IL-6 may be associated with cardiac electrophysiological abnormalities in COVID-19 patients." (PMID 40438117, 2025). "Elevated IL-6 levels were linked with augmented clinical severity regardless of vaccination status, indicating that anti-inflammatory treatment remains important even in vaccinated patients with COVID-19." (PMID 40868247, 2025). "However, elevated IL-6 levels are also linked to immune dysregulation in pediatric illnesses, such as Kawasaki Disease (KD), as well as in COVID-19, where high IL-6 levels are associated with worse clinical outcomes." (PMID 39775145, 2025). "IL-6 has also been linked to COVID-19 severity and mortality, indicating that this cytokine may play a crucial role as an inflammatory mediator in severe cases." (PMID 40647649, 2025). "Instead, interleukin-6 (IL-6) demonstrated high diagnostic accuracy for severe COVID-19." (PMID 40149726, 2025). "Elevated IL-6 has been consistently linked to stroke risk, and its association in our findings highlights the potential utility of inflammatory markers in predicting cerebrovascular complications among COVID-19 patients." (PMID 41362543, 2025). "Lately, increasing studies point out that the "cytokine storm," characterized by the intense release of TNF-α and IL-6, could contribute to the mortality caused by COVID-19." (PMID 39854441, 2025). "Similarly, the NSP9 and NSP10 proteins of SARS-CoV-2 induce overproduction of IL-6 and IL-8, which are the major causes of the cytokine storm in COVID-19 patients." (PMID 40313948, 2025). "Additionally, selenium’s ability to reduce inflammatory cytokines, such as IL-6, positions selenium as a key regulator in preventing cytokine storms—a significant cause of severe complications in COVID-19." (PMID 40416372, 2025). "This study further supports the use of IL-6 to discriminate patients with worse outcomes from COVID-19 and may be useful for identifying those at the highest risk for worse outcomes." (PMID 39969178, 2025). "Notably IL-6, a hallmark cytokine of acute COVID-19 which also contributes to the cytokine storm, and IL-6 remains elevated during sequelae." (PMID 39849406, 2025).